MIR19B2 (microRNA 19b-2)
Synonyms: hsa-mir-19b-2; MIRN19B2; miR-19b-2
Gene: MicroRNA gene on chromosome X (134,169,671 to 134,169,766, reverse strand). Ensembl gene ENSG00000284107.
Gene Ontology:
Biological process: miRNA-mediated post-transcriptional gene silencing
Cellular component: RISC complex
Homologues: Orthologues: chimpanzee ptr-mir-19b-2 (100% identical), macaque mml-mir-19b-2 (94% identical), pig ssc-mir-19b-2 (79% identical), mouse Mir19b-2 (78% identical), guinea pig MIR19B2 (76% identical), dog MIR19B-2 (60% identical), tropical clawed frog xtr-mir-19b-1 (58% identical). Paralogues in human: MIR19B1 (72% identical), MIR19A (53% identical).